PRAME (PRAME nuclear receptor transcriptional regulator)
Diseases named in the same sentence as PRAME in open-access papers (continued):
Sharing a sentence is not in itself a finding about the gene and the disease.
lung adenocarcinoma (4 papers, 2016 to 2023). A carcinoma that arises from the lung and is characterized by the presence of malignant glandular epithelial cells. "Taken together, our data demonstrate that PRAME plays a role in preventing the invasion and metastasis of lung adenocarcinoma and novel diagnostic or therapeutic strategies can be developed by targeting PRAME." (PMID 27391090, 2016). "Our results show that PRAME is downregulated in lung adenocarcinoma and lung bone metastasis compared with normal human lung." (PMID 27391090, 2016). "Taken together, our data suggest that PRAME serves as a tumor suppressor of lung adenocarcinoma via downregulating E-cadherin and MMP1-mediated migration, leading to the inhibition of EMT." (PMID 27391090, 2016). "In this study, we demonstrated that the expression of PRAME and E-cadherin was decreased in the human lung adenocarcinoma and lung bone metastases." (PMID 27391090, 2016). "PRAME has been recently introduced as a prognostic and/or oncogenic biomarker of various cancer types, including melanocytic neoplasms, invasive breast carcinoma, lung adenocarcinoma, lung squamous cell carcinoma, and hematological malignancies." (PMID 37796789, 2023). "The expression level of PRAME could be used as a biomarker in early detection, prognostication and mornitoring for recurrence of lung adenocarcinoma." (PMID 27391090, 2016). "Novel strategies might be developed to prevent EMT and metastasis of lung adenocarcinoma by targeting PRAME." (PMID 27391090, 2016). "After the identification of MMP1 as the downstream gene of PRAME, we further analyzed the clinical relevance of MMP1 in lung adenocarcinoma using the clinical data of lung adenocarcinoma patients." (PMID 27391090, 2016).
ovarian tumors (4 papers, 2023 to 2024). "In addition, PRAME was more expressed in tissues of ovarian-tumor-induced death cases compared with survival cases." (PMID 36980687, 2023). "The number of previously identified peptides derived from PRAME, CTCFL and CLDN6 binding in different common HLA class I molecules is limited, as well as solid evidence of processing and presentation in the context of HLA class I on ovarian tumors." (PMID 37026005, 2023).
rhabdomyosarcoma (4 papers, 2020 to 2025). A rare aggressive malignant mesenchymal neoplasm arising from skeletal muscle. "Currently, PRAME is a target antigen in a clinical phase I trial evaluating multi-tumour-associated antigen-specific cytotoxic T lymphocytes in rhabdomyosarcoma (NCT02239861, TACTASOM)." (PMID 33287125, 2020). "Clinical trials of cellular immunotherapy-targeting PRAME are currently ongoing in rhabdomyosarcoma (NCT02239861) and solid tumors (NCT02789228)." (PMID 38256198, 2024). "Immunoreactivity for PRAME may be helpful in some cases, however, PRAME positivity was seen in a subset of rhabdomyosarcomas (69% of cases positive, with 38% exhibiting 4+ staining), representing a potential pitfall." (PMID 40090763, 2025).
soft tissue sarcoma (4 papers, 2019 to 2025). A malignant neoplasm arising from muscle tissue, adipose tissue, blood vessels, fibrous tissue, or other supportive tissues excluding the bones. "Here, we show that PRAME is highly expressed in SS in comparison to other soft tissue sarcomas (STS) and is directly regulated by SS18-SSX, presenting a mechanism by which this fusion protein can drive oncogenesis." (PMID 39550391, 2024). "We, therefore, aimed to describe the expression of three CTAs, PRAME, NY-ESO-1, and SSX2, and analyze their prognostic value in a large cohort of high-risk soft tissue sarcomas with long-term follow-up." (PMID 33287125, 2020). "Our results, therefore, might help establish PRAME both as a prognostic marker that can be used in nomograms and as a valuable target antigen in soft tissue sarcoma." (PMID 33287125, 2020). "In the present study, we analyse the expression of CTAs NY-ESO-1, PRAME, and SSX2 in a large and well-characterised cohort of high-risk soft-tissue sarcoma patients with long-term follow-up and correlate our findings with the presence of TILs, clinical tumour characteristics, and survival data." (PMID 33287125, 2020). "In this study, we analysed the expression of CTAs PRAME, NY-ESO-1, and SSX2 as well as the presence of tumour-infiltrating lymphocytes (TILs) in a well-characterised cohort of high-grade soft tissue sarcoma patients." (PMID 33287125, 2020).
squamous cell carcinoma (4 papers, 2020 to 2025). A carcinoma arising from squamous epithelial cells. "Basal cell carcinomas (BCCs) and squamous cell carcinomas (SCCs) demonstrated weak to moderate nuclear staining for PRAME in >75% of cells." (PMID 39727621, 2024). "Our study also revealed distinct PRAME staining patterns in common skin cancers, namely basal cell carcinomas (BCCs) and squamous cell carcinomas (SCCs)." (PMID 39727621, 2024). "Two distinct research reports on non-small cell lung cancer (NSCLC) patients of Asia (South Korea, Singapore, Taiwan, and Thailand) showed a higher rate of PRAME transcripts in squamous cell carcinoma (SCC), and in smokers compared with non-smokers." (PMID 40961095, 2025). "A critical consideration is non-melanoma skin cancer (NMSC), where PRAME expression varies, with basal cell carcinoma (BCC) showing a higher expression than squamous cell carcinoma (SCC)." (PMID 38338862, 2024).
breast tumours (3 papers, 2013 to 2021). "In line with this, interrogation of TCGA and GTEx data demonstrated an increased PRAME expression in ovarian and esophageal tumor tissues in addition to breast tumors where it is associated with worse survival." (PMID 30602372, 2019). "Given the prognostic connotation of PRAME expression in immune‐unfavourable breast tumours, we sought to investigate the role of PRAME in modulating the tumour immune microenvironment and the anti‐tumour immune response." (PMID 34612587, 2021). "Consistent with reports that PRAME is expressed in breast tumours, PRAME was readily detected in MCF7 cells, by immunofluorescence staining, where it also showed a strong association with Golgi-like structures." (PMID 23460923, 2013).
desmoplastic melanoma (3 papers, 2022 to 2024). A melanoma of the skin characterized by a proliferation of atypical spindled melanocytes in the dermis, in a background of abundant collagen. "Desmoplastic melanoma, an invasive, neurotropic malignancy, was found to have PRAME positivity in only 35% of cases." (PMID 39451258, 2024).
Ewing sarcoma (3 papers, 2017 to 2026). A small round cell tumor that lacks morphologic, immunohistochemical, and electron microscopic evidence of neuroectodermal differentiation. "Another example is a 36-year-old patient with advanced Ewing sarcoma and a 210-fold (rank 2) increase in mRNA expression of the PRAME cancer testis antigen." (PMID 41554728, 2026). "Western blot analyses of SS18-SSX, PRAME, and EZH2 showed PRAME expression in translocation positive SS (TP-SS) and in other STS cells, including the RD-ES Ewing sarcoma cell line, while the SW982 translocation negative (TN-SS) cells had no detectable expression." (PMID 39550391, 2024).
head and neck squamous cell carcinoma (3 papers, 2021 to 2024). A squamous cell carcinoma that arises from any of the following anatomic sites: lip and oral cavity, nasal cavity, paranasal sinuses, pharynx, larynx, and salivary glands. "Especially, high PRAME expression plays an important role in head and neck squamous cell carcinoma, which is expected to be a novel therapeutic target and a biomarker of poor outcome." (PMID 36910848, 2023). "Furthermore, the increased expression of PRAME is a marker of poor prognosis in different types of neoplasias, namely, breast cancer, head and neck squamous cell carcinoma (HNSCC), neuroblastoma, osteosarcoma, among others." (PMID 35008260, 2021).
Hodgkins lymphoma (3 papers, 2013 to 2023). A heterogeneous group of malignant lymphoid neoplasms of B-cell origin characterized histologically by the presence of Hodgkin and Reed-Sternberg (HRS) cells in the vast majority of cases. "In contrast to sensitive cell lines, chemotherapy resistant Hodgkin lymphoma cell lines show an increased expression of PRAME." (PMID 23409080, 2013).
lymphoma (3 papers, 2022 to 2023). A malignant (clonal) proliferation of B- lymphocytes or T- lymphocytes which involves the lymph nodes, bone marrow and/or extranodal sites. "In this study, we showed that PRAME was involved in dual functions (cell extrinsic and intrinsic) during lymphoma pathogenesis." (PMID 35380993, 2022). "In turn, PRC2-regulated genes were repressed in isogenic PRAME-KO lymphoma cell lines, and PRAME was found to directly interact with EZH2 as a negative regulator." (PMID 35380993, 2022). "We then examined the spleens of these animals by IHC and observed that EZH2i induced PRAME expression in the treated lymphomas as compared with controls (P < 0.001)." (PMID 35380993, 2022). "In summary, we have revealed dual functions of PRAME in DLBCL, providing therapeutic rationales for treatment of high-risk patient populations in DLBCL, other lymphomas, and cancers in general that rely on immune escape phenotypes." (PMID 35380993, 2022). "Moreover, PRAME expression has been reported to be correlated with chemotherapy resistance in patients with UC and some malignant lymphomas." (PMID 38132219, 2023). "EZH2 inhibition induces PRAME expression and immune infiltrates in Ezh2-mutant lymphomas in vivo." (PMID 35380993, 2022). "The association of EZH2 with the PRAME promoter and the transcriptional repression of PRAME in EZH2-mut lymphomas prompted us to explore whether EZH2-targeted therapy might induce PRAME and reactivate antitumor immunity in vivo." (PMID 35380993, 2022). "In particular, our demonstration of dual functions of PRAME resulting in potentially synergistic therapeutic reversion of PRC2-mediated and immune escape mechanisms appears attractive in a subset of patients with lymphoma." (PMID 35380993, 2022).
melanocytic neoplasm (3 papers, 2022 to 2024). "PRAME has recently emerged as a novel immunohistochemical marker useful for the differential diagnosis of melanocytic neoplasms." (PMID 35328198, 2022).
skin cancer (3 papers, 2024 to 2025). "We examined the expression of PRAME in adnexal lesions and common skin cancers to determine whether it is of potential diagnostic utility in supporting the differentiation between sebaceous and non-sebaceous lesions." (PMID 39727621, 2024). "Consistent with several previous reports, in our cohort of skin tumors, PRAME protein expression was observed in AKs, Bowen's disease, cSCC and BCC, but not in normal skin." (PMID 40101298, 2025). "Preferentially Expressed Antigen in Melanoma (PRAME), a member of the cancer/testis antigen family, is central to the field of skin cancer diagnostics and therapeutics." (PMID 38338862, 2024).
angiosarcoma (2 papers, 2020 to 2023). A malignant tumor arising from the endothelial cells of the blood vessels. "Diffuse and strong PRAME expression was significantly more often encountered in spindle cell melanomas than in the other tumors, except angiosarcoma." (PMID 37373134, 2023).
B cell lymphomas (2 papers, 2022). "Our discovery that both genomic PRAME deletion and EZH2 mutations converge on reduced PRAME expression and downstream phenotypes underscores the pathogenic relevance of the PRAME gene in B cell lymphoma." (PMID 35838054, 2022).
chronic lymphocytic leukemia (2 papers, 2019 to 2024). "Although PRAME is widely believed to be an intracellular antigen, one study detected a membrane-bound form of PRAME in chronic lymphocytic leukemia and mantle cell lymphoma." (PMID 31311081, 2019).
Cutaneous T-Cell Lymphomas (2 papers, 2013 to 2021). "There have been no studies of PRAME expression in either cutaneous or non-cutaneous T-cell lymphoma." (PMID 35076507, 2021).
embryonal carcinoma (2 papers, 2008 to 2024). A non-seminomatous malignant germ cell tumor characterized by the presence of large germ cells with abundant cytoplasm resembling epithelial cells, geographic necrosis, high mitotic activity, and pseudoglandular and pseudopapillary structures formation. "Almost all testicular embryonal carcinomas lack PRAME expression." (PMID 38541782, 2024). "The function of the Pramel genes in embryonic development is unknown, but interestingly, PRAME inhibits retinoic-acid induced differentiation in mouse embryonic carcinoma F9 cells." (PMID 18500982, 2008). "Two embryonal carcinoma cell lines, 2102EP and NCCIT, which are naturally PRAME-negative and hypermethylated, revealed upregulated PRAME expression following treatment with various HDACIs." (PMID 38541782, 2024).
Fibroadenoma (2 papers, 2016 to 2020). A benign tumor of the breast characterized by the presence of stromal and epithelial elements. "Using machine learning to build predictive regression models, we selected a five-gene transcript set (ABCA8, APOD, CCL19, FN1, and PRAME) to discriminate between fibroadenomas and phyllodes tumors." (PMID 26961242, 2016). "In a separate study by Kuijper interrogating the transcriptome differences between five fibroadenomas and eight phyllodes tumors, CTAG1/2, PRAME, HOXC13, ELF5 and FABP7 were among 96 other transcripts found to be highly differentially expressed between fibroadenomas and phyllodes tumors." (PMID 26961242, 2016).
gastric cancer (2 papers, 2023 to 2025). A primary or metastatic malignant neoplasm involving the stomach. "PRAME expression was also found to be associated with the malignant potential of gastric cancer via bioinformatics data analysis and was found to be a poor prognostic marker of liver cancer, promoting liver cancer cell proliferation and inhibiting cell apoptosis." (PMID 36980687, 2023). "Tumor cell regions were demarcated using gastric cancer-specific marker genes (KRT17/PRAME/GNGT1/GJB5/PI3)." (PMID 40452847, 2025).
germ cell tumors of the testis (2 papers, 2022 to 2023). "PRAME is a cancer-testis antigen expressed in a variety of tumors and plays a central role in the development of germ cells and the pathogenesis of testicular germ cell tumors." (PMID 37762707, 2023).
glioblastoma (2 papers, 2023 to 2024). The most malignant astrocytic tumor (WHO grade IV). "Kaplan-Meier analysis stratified by revised classification showed that PRAME positivity was solely associated with IDH-wildtype glioblastoma, grade 4." (PMID 37796789, 2023). "Finally, PRAME expression status was identified as an independent prognostic factor of IDH-wildtype glioblastoma." (PMID 37796789, 2023). "However, PRAME positivity was of prognostic significance in IDH-wildtype glioblastoma grade 4 (p = 0.018)." (PMID 37796789, 2023). "In the present study, we showed that PRAME expression status was significantly correlated with biological and clinicopathological characteristics of adult glioma grade 4, IDH-wildtype (IDH-wildtype glioblastoma)." (PMID 37796789, 2023). "PRAME expression statuses may dictate different biological and clinicopathological profiles in IDH-wildtype glioblastoma." (PMID 37796789, 2023). "PRAME-positive tumors had different biological (gene expression, DNA methylation, and pathway) and clinicopathological characteristics, which were related to IDH-wildtype glioblastoma." (PMID 37796789, 2023).
glioma (2 papers, 2022 to 2023). A benign or malignant brain and spinal cord tumor that arises from glial cells (astrocytes, oligodendrocytes, ependymal cells). "We aimed to perform a comprehensive analysis to explore PRAME gene expression and its biological and clinicopathological significance in gliomas." (PMID 37796789, 2023). "Our study showed that PRAME-positive gliomas were distributed more densely in the IDH-wildtype-related methylation cluster compared to the other cluster." (PMID 37796789, 2023). "In DNA methylation analysis, PRAME-positive gliomas were distributed more densely in a distinct, grade 4-related cluster, which implied that PRAME expression can be an indicator of the CpG methylation landscape." (PMID 37796789, 2023). "In general, gliomas grade 4 had higher PRAME expression compared to other categories." (PMID 37796789, 2023). "However, little is known about the biological and clinical significance of the PRAME protein and its corresponding gene in glioma." (PMID 37796789, 2023). "The biological and clinicopathological implications of PRAME expression have been unknown in adult gliomas." (PMID 37796789, 2023). "The PCA of the PanCancer Pathways panel showed that different PRAME expression status was relatively different in their distributions, indicating that PRAME positivity may be related to oncogenic mechanisms in adult glioma." (PMID 37796789, 2023). "Interestingly, we found that PRAME gene overexpression, which is more likely visualized by the protein expression detection methods, was related to a subgroup with a significantly worse prognosis than PRAME-low gliomas despite its small sample size." (PMID 37796789, 2023). "Therefore, examining whether there is a relationship between PRAME expression status and DNA methylation characteristics can further consolidate PRAME value in glioma biology." (PMID 37796789, 2023). "Further studies to validate PRAME protein expression in glioma, using western blot analysis, immunohistochemistry, immunofluorescence, or other techniques, are needed because it is not clear whether PRAME gene expression can be an indicator of its protein status." (PMID 37796789, 2023). "First, we defined PRAME overexpression when FPKM > 1, which was observed in only 14 gliomas within the entire studied cohort." (PMID 37796789, 2023). "Our study illustrated that a proportion of glioma did not express PRAME while the majority of glioma expressed PRAME, among which a few tumors possessed high PRAME expression." (PMID 37796789, 2023). "In gene expression analysis, there was a large number of gliomas showing no PRAME expression while a few numbers of tumors possessed high levels of PRAME expression." (PMID 37796789, 2023). "We explored the normalized read count value of these 668 gliomas and found that the PRAME gene was not expressed in 170 gliomas (PRAME-negative; FPKM = 0)." (PMID 37796789, 2023). "Using this panel, our PCA analysis illustrated that PRAME expression status can be a biomarker of glioma biology although further interpretations are not available in such general results." (PMID 37796789, 2023). "Among the 10 candidates, high mRNA expression of CCL8, FCGR2B, and TUBA4A and low mRNA expression of GABRD, PRAME, and SYN1 were significantly correlated with worse prognosis, while the mRNA expression of CCL18, SCN1B, SNCB, and VSNL1 showed no connection to the overall survival of glioma patients." (PMID 36685974, 2022). "However, various oncogenic processes or signals in PRAME-positive gliomas such as E2F targets, G2M mitotic checkpoint, reactive oxidative oxygen species, IL6-JAK-STAT6, angiogenesis, epithelial-mesenchymal transition, and mTORC1 were activated at the lower levels compared to PRAME-negative tumors." (PMID 37796789, 2023).
keratinocyte carcinoma (2 papers, 2025). A skin cancer arising from the keratin-producing cells of the epidermis. "A large-scale study to examine the responses of keratinocyte carcinomas with differences in PRAME expression to immunotherapy will be necessary to further examine this divergence in response to treatment." (PMID 40933628, 2025).